IL6 (interleukin 6)
Diseases named in the same sentence as IL6 in open-access papers (continued):
Sharing a sentence is not in itself a finding about the gene and the disease.
plasma cell tumors (19 papers, 2007 to 2025). "Among the molecular mediators, interleukin-6 (IL-6) has emerged as a key growth factor in plasma cell dyscrasias." (PMID 40757112, 2025). "It is known that the IL-6 signalling complex is involved in haematological malignancies, markedly in B-cell-derived and plasma cell tumours." (PMID 38542233, 2024). "Exposure of human vascular endothelial cells to VEGF increased the expression of IL-6 in plasma cell disorders." (PMID 35133575, 2022). "There is also evidence for cooperation of interleukin-6 (IL-6) with Myc in plasma cell tumor development." (PMID 26327622, 2015). "As the cytokine interleukin-6 (IL-6) is important for the differentiation and survival of plasma cells, and Pirh2−/− mice develop a plasma cell disorder, we next examined by ELISA the serum level of IL-6 in Pirh2−/− mice and their controls." (PMID 22125490, 2011). "In MM, Osteolytic lesions are found only adjacent to intramedullary plasma cell foci or plasma cell tumors, indicating that MM cells may release factors (such as RANKL or IL-6) that trigger the activation of OC." (PMID 36251145, 2023).
Sleep disturbance (19 papers, 2015 to 2025). An abnormal pattern in the quality, quantity, or characteristics of sleep. "The inflammatory cytokines, IL-6 and TNFα, were the most strongly associated with deployment-related pathology like more severe PTSD, problem drinking, increased neurobehavioral symptoms, and sleep dysfunction, as well as maladaptive functional outcomes." (PMID 35217643, 2022).
temporal lobe epilepsy (19 papers, 2008 to 2025). A localization-related (focal) form of epilepsy characterized by recurrent seizures that arise from foci within the temporal lobe, most commonly from its mesial aspect. "IL-6 is also thought to play a critical role in seizure development, and elevated IL-6 has been observed in patients with temporal lobe epilepsy, pediatric epilepsy, and electrical status epilepticus in sleep (ESES)." (PMID 32552898, 2020). "In human temporal lobe epilepsy, a variety of cytokines such as IL-1b, IL-6 and IL-ra are upregulated in the cerebrospinal fluid (CSF) in human temporal lobe epilepsy." (PMID 19787089, 2008). "Additionally, an increase in cell‐free DNA and IL‐6 has been observed in patients with focal epilepsy while chronic over production of IL‐6 is a characteristic of temporal lobe epilepsy." (PMID 25627810, 2015). "In addition, a significant increased serum level of IL-6, and total numbers of leukocytes, lymphocytes, neutrophils, and natural killer cells were measured during the first minutes of the postictal phases after seizures in patients with temporal lobe epilepsy." (PMID 26450065, 2015). "Pro-inflammatory cytokines — including interleukin-1β (IL-1β), interleukin-6 (IL-6), and tumor necrosis factor-α (TNF-α) — are significantly elevated in the serum and cerebrospinal fluid of patients with temporal lobe epilepsy and related syndromes." (PMID 40821023, 2025). "Elevated levels of IL-6 are observed in TBI patients and are considered to play a significant role in those with temporal lobe epilepsy and pediatric epilepsy." (PMID 36767668, 2023). "In patients with drug-resistant temporal lobe epilepsy (DRTLE), the neocortical levels of NFkB (nuclear factor kappa-light-chain-enhancer of activated B cells) and IL-6 were increased." (PMID 33377994, 2021). "Other studies have reported increased interictal levels of IL-6 in temporal lobe epilepsy (TLE) but not in extra-temporal lobe epilepsy (XTLE) or increase of IL-6, IL-17 and interferon-y (IFN-y) in TLE but only IL-17 and IFN-y in XTLE." (PMID 36895367, 2023). "Based on our previous findings, patients with refractory temporal lobe epilepsy (TLE) had chronically increased concentrations of the proinflammatory cytokine IL-6 in their serum compared with those in healthy controls; these patients also had a postictal increase in plasma IL-6." (PMID 32532251, 2020). "However, levels of IL-6 were also increased in both patient populations when compared to the control individuals, and were significant for the OV+EpNd patients (EpNd versus CTRL p = 0.077) in line with previous findings connecting elevated IL-6 plasma levels to temporal lobe epilepsy." (PMID 37535695, 2023).
Ventricular arrhythmia (19 papers, 2010 to 2025). "Studies have demonstrated that elevated TNF-α levels correlate with increased risk of ventricular arrhythmias, while IL-6 and IL-1β promote atrial remodeling, which predisposes individuals to AF." (PMID 40901119, 2025). "For example, what are the unique electrophysiological features (including ECG phenotypes and cellular channel biophysics) of IL-6 trans-signaling-linked ventricular arrhythmias?" (PMID 39125976, 2024). "Over the last decade, increasing evidence has been found to support IL-6 signaling as a powerful predictor of the severity of heart diseases and increased risk for ventricular arrhythmias." (PMID 39125976, 2024). "IL-6 increases ICa,L (which increases calcium load in myocytes and can be associated with ventricular arrhythmia), with IKr, IKs, and INa inhibited by IL-6, altogether leading to the prolongation of APD." (PMID 39125976, 2024). "QT interval is increased by +36% and +53%, for IL-6 and IL-6 + IL-6R, respectively, consistent with the signature high risk proarrhythmic effect that underlie fatal ventricular arrhythmias in patients." (PMID 34681909, 2021). "Ventricular arrhythmia incidence is associated with significantly elevated proinflammatory markers such as IL-6 and high-sensitive CRP in implantable cardioverter-defibrillator (ICD) patients with structural heart disease." (PMID 22203916, 2011). "Ventricular arrhythmia (VA) occurrence is associated with significantly elevated proinflammatory markers such as IL-6 and highly sensitive C-reactive protein (hs-CRP) in implantable cardioverter-defibrillator (ICD) patients with structural heart disease." (PMID 20885777, 2010). "Risk of ventricular arrhythmias has also been reported in patients with infectious diseases, and this risk may have been associated with high levels of interleukin-6 (IL-6)." (PMID 40507768, 2025). "Although IL-6 is known to play a prominent role in the pathogenesis and prognosis of ventricular electrical remodeling and in the future development of ventricular arrhythmia events, the mechanisms underlying its action on cardiomyocytes and in the heart are relatively unexplored." (PMID 39125976, 2024). "In the peri-shock period, increased IL-6 and IL-10 serum concentrations and changes in 5-diff blood count (increased neutrophils and decreased eosinophils) are observed, which may be associated with a higher risk of ventricular arrhythmia in HF patients." (PMID 41574188, 2025). "Thus elevated IL-6 levels, reduced IKr and associated action potential prolongation described here may contribute to delayed repolarization and associated ventricular arrhythmias such as TdP reported in patients with autoimmune inflammatory disorders." (PMID 30521586, 2018). "Without such information, the promise of a novel class of anti-IL-6 therapies for the treatment of human ventricular arrhythmia will likely remain unfulfilled." (PMID 39125976, 2024). "Cytokines present in the myocardium, including IL-1β, TNF-α, and IL-6, have even resulted in life-threatening ventricular arrhythmias through modulation of potassium and calcium channels." (PMID 33291425, 2020). "However, there is a paucity of mechanism-based pathological IL-6 trans-signaling processes in ventricular arrhythmia studies." (PMID 39125976, 2024). "Therefore, it would also be valuable to explore the link between IL-6 + IL-6R, IKs and ventricular arrhythmias." (PMID 34681909, 2021). "This strengthens the hypothesis that IL-6 may have a significant arrhythmogenic role in the general population, with baseline inflammatory status potentially exerting an even greater influence on the postoperative burden of ventricular arrhythmias." (PMID 41010936, 2025).
alcoholism (18 papers, 2015 to 2025). "Alcohol-induced hepatotoxicity can cause the nuclear translocation of NF-κB (p65), leading to the transcription of inflammatory genes such as IL-1B, IL-6, and TNFA." (PMID 38681193, 2024). "ELISA analysis indicated that SERPINA3 and IL-6 concentrations were significantly elevated in patients with alcohol dependence than in healthy controls (P < 0.001)." (PMID 35095596, 2021). "We recruited 58 individuals with alcohol dependence and 20 healthy controls to validate the hypothesis that SERPINA3 and IL-6 were dysregulated in individuals with alcohol dependence." (PMID 35095596, 2021). "This receptor is part of the pro-inflammatory cytokine IL-6 pathway that has been involved in the neuroimmune response to alcohol and may play a critical role in alcohol dependence." (PMID 34573170, 2021). "Recent data suggests that for individuals who meet criteria for alcohol abuse (based on the Michigan Alcohol Screening Test), black individuals demonstrate higher urine norepinephrine, serum C-reactive protein, and serum interleukin-6 levels compared to white individuals." (PMID 31568479, 2019). "Based on these findings, we hypothesized that taVNS could ameliorate PAWS in alcohol-dependent patients, the mechanism of which may be related to its regulation of plasma BDNF, IL-6, TNF-α, and leptin levels." (PMID 34526917, 2021). "The goal of this study was to evaluate the effect of transcutaneous auricular vagus nerve stimulation (taVNS) on PAWS and plasma brain-derived neurotrophic factor (BDNF), interleukin-6 (IL-6), tumor necrosis factor-α (TNF-α), and leptin levels in patients with alcohol dependency." (PMID 34526917, 2021). "One study observed that the levels of serum IL-6 in patients with alcohol dependence did not significantly decrease although they showed a trend from baseline to 16-week follow-up (p = 0.052)." (PMID 32260096, 2020). "Plasma leptin concentrations were positively correlated with the plasma IL-6, CRP, and TNF-α levels in the present study, which suggests that the role of leptin as a marker of addiction in alcohol-dependent patients may be related to the changes in inflammatory cytokines." (PMID 32265847, 2020). "Non-responders (DAS28-ESR > 3.2) had a lower frequency of alcoholism (p < 0.04), a higher functional disability score (p < 0.01), and higher ESR, CRP (p < 0.01 and p < 0.05, respectively), and IL-6 levels (p < 0.002) in comparison to responders." (PMID 40362255, 2025).
aspergillosis (18 papers, 2015 to 2025). Aspergillosis is an infection, growth, or allergic response caused by the Aspergillus fungus. "Tocilizumab, an interleukin-6 (IL-6) receptor antagonist, demonstrated the strongest association with fungal pneumonia, specifically COVID-19-associated pulmonary aspergillosis (CAPA) and cryptococcosis." (PMID 41190068, 2025). "IL-6 levels are elevated in asthmatic sputum samples, whilst IL-6 deficiency in mice is associated with increased susceptibility to aspergillosis." (PMID 34200666, 2021). "Meanwhile, IL-6 inhibitors contribute to the development of Aspergillosis by inhibiting Th17 cell development, which is part of the immune response against Aspergillus fumigatus." (PMID 38205484, 2023). "The cytokines IL-6 and TNF play a key role in anti-Aspergillus immunity with mice deficient in either cytokine possessing an increased susceptibility to Aspergillosis." (PMID 34975870, 2021). "In recent years, there has been an increasing amount of literature on cytokine levels in IPA patients, including elevated IL-6 and IL-8 levels in serum or BAL of aspergillosis patients." (PMID 35205926, 2022). "However, cases of influenza-associated aspergillosis are usually more likely to have H1N1 subtypes and higher levels of C-reactive protein and interleukin-6 than cases without aspergillosis." (PMID 35628717, 2022).
bronchiectasis (18 papers, 2007 to 2025). Segmental, irreversible dilation of the bronchial tree resulting in the accumulation of secretions which leads to obstruction. "Further, the expression of MIP-1α and MCP-1 by macrophages, T cells, monocytes, and other inflammatory cells enhanced the release of IL-6 or IL-8, which contributed to the pathogenic process of bronchiectasis." (PMID 35755996, 2022). "Airway inflammation in bronchiectasis is characterised by neutrophil-dominated inflammation associated with elevated levels of proinflammatory cytokines and chemokines such as IL-8, IL-6 and TNF-α in bronchoalveolar lavage fluid (BALF)." (PMID 25822228, 2015). "In general, we speculate that the curative mechanisms of BMGLF in bronchiectasis are primarily associated with the expressional regulation of inflammatory factors such as IL6, IL10, MMP9, CXCL8, MAPK1, and ICAM1." (PMID 33488758, 2021). "Compared to that of the controls, the levels of interleukin (IL)-6 (p<0.001), IL-10 (p<0.001), carbonylated proteins (p=0.001), and superoxide anions (p=0.046) were significantly increased in adults with bronchiectasis." (PMID 33886789, 2021). "The present study showed that compared to healthy controls, adults with bronchiectasis who were clinically stable presented increased levels of IL-6, IL-10, carbonylated proteins, and superoxide anion, and decreased catalase activity." (PMID 33886789, 2021). "Proinflammatory cytokines, such as TNF-α, IL-6, IL-8, and IL-1b, were studied, as they have been found elevated in sputum or bronchoalveolar damage in bronchiectasis patients." (PMID 32823681, 2020). "At 30 days, severe exacerbations were independently associated with higher levels of IL-17 (Odds ratio (OR) 4.58), IL-6 (OR 4.89), IL-8 (OR 3.08), and hsCRP (OR 6.7), adjusted for age, the bronchiectasis severity index, and treatment duration." (PMID 32823681, 2020). "In CF bronchiectasis, Nixon and co-authors demonstrated that IL-6 sputum levels were negatively associated with FEV1 and forced vital capacity (FVC) with IL-6 decreasing after antibiotic treatment." (PMID 30380761, 2018). "IL-6 and IL-10 levels were increased in adults with bronchiectasis." (PMID 33886789, 2021). "IL-6 and IL-8 levels were significantly increased in the sputum and BALF of bronchiectasis patients, and neutrophil influx was induced." (PMID 36902466, 2023). "There were significant differences in cytokine (IL-8, IL-1β, IL-6, TNF-α, IL-12) levels of BAL fluid between patients with bronchiectasis and healthy controls." (PMID 17224076, 2007). "The BAL fluid levels of the cytokines (IL-8, IL-1β, IL-6, TNF-α, IL-12) were found to be significantly elevated in patients of bronchiectasis when compared with controls (p < 0.0001)." (PMID 17224076, 2007). "Significantly elevated levels of proinflammatory IL-6, TNF-α, and IL-12 were likewise noted in cases with bronchiectasis versus healthy controls." (PMID 17224076, 2007). "Also a heterogeneity of systemic inflammation was found in bronchiectasis, with higher levels of CRP, IL-6 and plasma fibrinogen during an exacerbation." (PMID 37118704, 2023). "Another study found that IL-6 levels were elevated in the sputum from children with non-CF bronchiectasis compared to sputum from children with CF and healthy adult controls." (PMID 36505420, 2022). "By mapping drug targets to disease targets, we identified 51 common targets, including IL10, TLR2, STAT3, IL6, and CXCL8, which served to indicate putative pathways whereby BMGLF could be used to treat bronchiectasis." (PMID 33488758, 2021). "The current data demonstrate highly significant increases in all Th17 pathway-associated chemokines and cytokines measured in the airways of adult bronchiectasis subjects, including pathway effectors (IL-17A, IL-6, IL-8 and TNF-α) and regulators (IL-1α, IL-1β, IL-6 and IL-23)." (PMID 25822228, 2015).
bronchiectasis (continued). "For example, IL6 and IL8 are key cytokines involved in neutrophil recruitment to the airway, and such recruited cells could have both beneficial (contributing to NTM killing) and detrimental (involvement in tissue damage and bronchiectasis) effects." (PMID 40635565, 2025). "Compared to normal controls, subjects with non-CF bronchiectasis also had highly significantly elevated BALF levels of all measured Th17 pathway cytokines (IL-1α, IL1β, IL-6, IL-8, IL-23 and TNF-α (p<0.0001 for all)." (PMID 25822228, 2015). "The most comprehensive BALF study in adult non-CF bronchiectasis demonstrated increased levels of neutrophil elastase, myeloperoxidase, TNF-α, IL-6 and IL-8 but not IL1β compared to controls." (PMID 25822228, 2015).
bronchopulmonary dysplasia (18 papers, 2010 to 2025). Bronchopulmonary dysplasia is a chronic respiratory disease that results from complications related to lung injury during the treatment of infant acute respiratory distress syndrome in low-birth-weight premature infants or from abnormal lung development in older infants. "Elevated levels of IL-6 in cord blood are associated with an increased risk of bronchopulmonary dysplasia (BPD) in neonates." (PMID 40244141, 2025). "This supports the theory that development of fetal inflammatory response (as defined by plasma IL-6 concentration) is associated with inflammation/injury of fetal lungs in utero, which results in bronchopulmonary dysplasia." (PMID 38001923, 2023). "This topic should be of interest because elevated levels of interleukin-6 and placental histology were noted, showing that the risk of systemic inflammation (41.3% vs. 25.7%; p = 0.007), funisitis, and bronchopulmonary dysplasia (26.8% vs. 10.1%; p = 0.0001) is significantly higher in neonates." (PMID 33652790, 2021). "Very low birth weight infants have increased concentrations of the proinflammatory cytokines IL-8, IL-1β, IL-6 and MCP-1 in tracheal aspirates and their levels were associated with the risk of bronchopulmonary dysplasia." (PMID 35725416, 2022). "Like preterm sheep, ventilated very low birth weight (VLBW) infants have increased concentrations of the pro-inflammatory cytokines IL-8, IL-1β, IL-6, and MCP-1 in tracheal aspirates and these increased levels correlate with an increased risk of bronchopulmonary dysplasia (BPD)." (PMID 21034485, 2010). "Additionally, IL-6 is an independent predictor of adverse neonatal outcomes, including bronchopulmonary dysplasia (BPD) and white matter injury (WMI) in preterm infants." (PMID 40640885, 2025). "As a therapeutic tool, caffeine is used to treat apnea of prematurity in preterm newborn infants, and it has been found to reduce bronchopulmonary dysplasia (BPD), a chronic lung disease of preterm infants, by reducing pulmonary inflammation, including IL-6 and TNF-α secretion." (PMID 34371919, 2021).